TUBB (tubulin beta class I)
Description:
Tubulin is the major constituent of microtubules, a cylinder consisting of laterally associated linear protofilaments composed of alpha- and beta-tubulin heterodimers. Microtubules grow by the addition of GTP-tubulin dimers to the microtubule end, where a stabilizing cap forms. Below the cap, tubulin dimers are in GDP-bound state, owing to GTPase activity of alpha-tubulin.
Synonyms: TUBB5; OK/SW-cl.56; MGC16435; M40; CDCBM6; CSCSC1; TUBB1
Tractability: Small molecule: an approved drug acts on it; a structure with a bound ligand is known; a high-quality ligand is known; it belongs to a druggable protein family. Antibody: its Gene Ontology location is reachable by antibodies, with high confidence. PROTAC: UniProt records ubiquitination sites on it; ubiquitination databases record sites on it; its protein half-life has been measured; a small molecule that binds it is known. Other modalities: an approved drug acts on it.
Target class: Structural protein
Chemical probes: ELEUTHEROBIN (high quality), PACLITAXEL (high quality)
Gene: Protein-coding gene on chromosome 6 (30,717,435 to 30,725,538, forward strand). Ensembl gene ENSG00000196230.
Subcellular location: Cytoplasm, cytoskeleton
Subcellular location (Human Protein Atlas): Microtubules; Basal body; Cytokinetic bridge; End piece; Flagellar centriole; Mitotic spindle; Primary cilium; Primary cilium tip; Principal piece
Pathways (Reactome):
Cell Cycle: AURKA Activation by TPX2; Loss of Nlp from mitotic centrosomes; Loss of proteins required for interphase microtubule organization from the centrosome; Recruitment of NuMA to mitotic centrosomes; Recruitment of mitotic centrosome proteins and complexes; Regulation of PLK1 Activity at G2/M Transition
Disease: Potential therapeutics for SARS
Immune System: Neutrophil degranulation
Organelle biogenesis and maintenance: Anchoring of the basal body to the plasma membrane
Gene Ontology:
Molecular function: MHC class I protein binding; protein binding; ubiquitin protein ligase binding; GTP binding; structural constituent of cytoskeleton; structural molecule activity; GTPase activating protein binding; GTPase activity; protein domain specific binding; protein-containing complex binding
Biological process: odontoblast differentiation; cell division; cytoskeleton-dependent intracellular transport; microtubule-based process; mitotic cell cycle; natural killer cell mediated cytotoxicity; cytoskeleton organization; regulation of synapse organization
Cellular component: cell body; ciliary tip; cilium; cytoplasm; cytoplasmic ribonucleoprotein granule; extracellular exosome; intercellular bridge; microtubule; microtubule cytoskeleton; mitotic spindle; nuclear envelope lumen; nucleus; sperm end piece; sperm principal piece; azurophil granule lumen; cytoskeleton; cytosol; extracellular region; membrane raft; protein-containing complex
Genetic constraint (gnomAD): Loss-of-function variants: 2 observed, 35.45 expected, observed/expected ratio (o/e) 0.0564, 90% interval 0.022 to 0.18. The upper end of that interval is the gene's LOEUF score, 0.18, which puts it in group 1 of 6, group 1 being the genes least tolerant of losing a copy. Missense variants: 50 observed, 618.86 expected, observed/expected ratio (o/e) 0.0808, 90% interval 0.063 to 0.1. Synonymous variants: 204 observed, 226.76 expected, observed/expected ratio (o/e) 0.9, 90% interval 0.8 to 1.01.
Homologues: Orthologues: chimpanzee TUBB (100% identical), guinea pig TUBB (100% identical), mouse Tubb5 (100% identical), pig TUBB (100% identical), rat Tubb5 (100% identical), rabbit TUBB (99% identical), zebrafish tubb5 (99% identical), macaque TUBB (98% identical), tropical clawed frog tubb (96% identical). Paralogues in human: TUBB4B (98% identical), TUBB4A (96% identical), TUBB2B (96% identical), TUBB2A (95% identical), TUBB3 (92% identical), TUBB6 (91% identical), TUBB8 (89% identical), TUBB8B (87% identical), TUBB1 (79% identical), TUBA1B (43% identical), TUBA4A (43% identical), TUBA1A (43% identical), and 11 more.
Diseases named in the same sentence as TUBB in open-access papers:
TUBB is named in the same sentence as 87 diseases in open-access papers, as found by Europe PMC text mining. Sharing a sentence is not in itself a finding about the gene and the disease. The quoted sentences say what the papers report.
breast carcinoma (9 papers, 2017 to 2025). "GEPIA and Breast Cancer Gene-Expression Miner were used to explore TUBB expression in breast cancer patients." (PMID 36140469, 2022). "Significantly higher TUBB mRNA was observed in breast cancer tissue compared to tumor-adjacent and normal tissue." (PMID 36140469, 2022). "The mRNA expression of TUBB in breast cancer was investigated using several bioinformatic platforms including GEPIA and bc-GenExMiner." (PMID 36140469, 2022). "In this research, the expression of TUBB in breast cancer was explored using two different platforms including GEPIA and bc-GenExMiner." (PMID 36140469, 2022). "In the databases, significantly higher TUBB mRNA expression in breast cancer patients was observed, compared to normal breast tissue." (PMID 36140469, 2022). "Although high TUBB mRNA levels correlate with poor prognosis in renal and liver cancer, its correlation with breast cancer outcome remains to be investigated." (PMID 36140469, 2022). "Significant positive correlation was observed between TUBB mRNA and lymph nodes examined positive in ERα-positive breast cancer patients." (PMID 36140469, 2022). "It has been shown recently that TUBB mRNA expression is upregulated in breast cancer patients resistant to chemotherapy." (PMID 36140469, 2022). "Among them, 5 (TOP2A, HER3, CDC25B, MCM2 and TUBB) are from breast cancer cell lines and, in particular, HER2 positive cells (ZR7530 is [ER+PR−]HER2+, HCC2218 and BT474 are [ER−PR−]HER2+78)." (PMID 28754978, 2017). "Previous studies have revealed the role of TUBB as a prognostic marker in pan-cancer, including breast cancer, and its carcinogenic role with miR-195 in lung cancer, but its role in CRC remains unclear." (PMID 40539065, 2025). "Whether any of the other genes highlighted, such as TUBB, that has recently been identified as a prognostic marker for ER alpha positive breast cancers, play a role in this syndrome is yet to be determined." (PMID 37456561, 2023). "The analysis showed that significantly higher TUBB mRNA expression in breast cancer patients was observed compared to normal breast tissue, suggesting that the expression of TUBB might predict the prognosis of breast cancer." (PMID 36140469, 2022). "In addition, the results showed that TUBB might mediate the development of metastasis in ERα-positive breast cancer patients possibly through the TSC/mTOR pathway." (PMID 36140469, 2022). "Additionally, TUBB has been shown to be involved in the breast cancer cell cycle." (PMID 36140469, 2022). "Many of these are enzymes or cytoskeletal proteins (ANXA1, KRT10, KRT16, TUBB, ACTB, ACTA1, PKM2, and HSPA8) that have been previously reported as able to induce autoantibodies with diagnostic potential across different tumor types, including PDAC, breast cancer, and neuroblastoma." (PMID 30651550, 2019). "The genes that show significant positive correlation with TUBB and show a similar KM plot pattern (worse OS, RFS, and DMFS) in ERα-positive breast cancer patients were selected." (PMID 36140469, 2022). "Approved drugs that directly target TUBB were identified using DRUGSURV; three out of the six drugs that directly target TUBB are approved in breast cancer treatment including vinblastine, vincristine, and vinorelbine." (PMID 36140469, 2022). "TUBB, which interacts with CAND1, has also been shown to correlate with poor OS in ERα-positive breast cancer." (PMID 36292029, 2022). "The heatmap also highlights genes previously characterized within breast cancer, however not in the context of a potential therapeutic target, for example, TUBB." (PMID 36598637, 2023). "Kaplan–Meier Plotter was used to assess the relationship between TUBB expression and several prognostic indicators including overall, distant metastasis-free, and relapse-free survival in ERα-positive and ERα-negative breast cancer." (PMID 36140469, 2022).
breast carcinoma (continued). "The genes that correlate with TUBB in ERα-positive and ERα-negative breast cancer were explored and the pathways were investigated using GSCA." (PMID 36140469, 2022). "Significant positive correlations were observed between TUBB and gene markers of immune cells in ERα-positive breast cancer patients, whereas significant negative correlations were observed in ERα-negative breast cancer patients." (PMID 36140469, 2022). "In contrast, the correlation between TUBB mRNA and lymph nodes examined positive was not significant in ERα-negative breast cancer patients." (PMID 36140469, 2022). "Although the correlation between TUBB and prognosis was not studied extensively in breast cancer, several published report showed that TUBB mRNA expression significantly correlates with worse OS in lung adenocarcinoma, renal, and liver cancer patients." (PMID 36140469, 2022). "The KM plotter website was utilized to assess the prognostic value of the TUBB gene in ERα-positive and ERα-negative breast cancer patients." (PMID 36140469, 2022). "ERα-positive breast cancer patients with increased TUBB showed worse prognosis, possibly through the activation of the TSC/mTOR pathway, whereas ERα-negative breast cancer patients with increased TUBB mRNA showed better prognosis." (PMID 36140469, 2022). "Moreover, three top genes EZR (ranked 12th), TUBB (ranked 27th), and RDX (ranked 36th), were shown to be involved in organization and regulation of morphological characteristics of breast cancer cells including cell shape and membrane to membrane docking." (PMID 28133571, 2017). "Genes enriched in the top breast cancer cell lines are TOP2A, HER3, CDC25B, MCM2 and TUBB." (PMID 28754978, 2017). "Additionally, the genes that show significant negative correlation with TUBB in ERα-positive and ERα-negative breast cancer and that show the opposite KM plots were also selected." (PMID 36140469, 2022). "The analysis revealed that TUBB might be considered as a predictive biomarker for worse prognosis in ERα-positive and better prognosis in ERα-negative breast cancer." (PMID 36140469, 2022). "However, further experiments should be carried out to further explore the role of TUBB in ERα-positive and ERα-negative breast cancer." (PMID 36140469, 2022). "Neoplasmic histologic grade 3 showed significantly higher TUBB mRNA compared to grade 2 in ERα-negative breast cancer patients, whereas the differences between grades 3 and 1 and between grades 2 and 1 were not significant in ERα-negative breast cancer patients." (PMID 36140469, 2022). "Moreover, the genes that show significant negative correlation with TUBB and show opposite KM plot pattern (better OS, RFS, and DMFS) in ERα-positive breast cancer patients were also selected." (PMID 36140469, 2022).
E. coli infection (6 papers, 2015 to 2024). "Our study is the first article to discuss the influence of the gut microbes on clinical outcomes of PC by bioinformatic analysis and the first article to deduce that TUBB plays a vital role in pathogenic E. coli infection by regulating TUBB/Rho/ROCK signaling." (PMID 32461969, 2020). "TUBB (tubulin, beta class I) may be associated with the pathogenic E. coli infection, which may be involved in the carcinogenesis and progression of PC by activating the TUBB/Rho/ROCK signaling pathway." (PMID 39346734, 2024). "Survival analysis and pathway analysis revealed that TUBB (tubulin, beta class I) may be associated with the pathogenic E. coli infection, which may be involved in the carcinogenesis and progression of PC by activating the TUBB/Rho/ROCK signaling pathway." (PMID 32461969, 2020). "The study done by Luo and colleagues identified the gene TUBB (tubulin, beta class I) as having an association with pathogenic E. coli infection, which can activate the TUBB/Rho/ROCK signaling pathway and might thus participate in the development and carcinogenesis of PC." (PMID 38183010, 2024). "Therefore, we assumed that the pathogenic E. coli infection may induce the expression of TUBB and then stimulates its downstream signaling Rho/ROCK pathway, which eventually promotes the progression of PC." (PMID 32461969, 2020). "Enrichment analysis using the KEGG database revealed the significant participation of detected proteins in pathogenic E. coli infection (ACTG1, TUBA1C, TUBA4A, TUBB, TUBB8, and YWHAZ), which may indicate microbiota changes associated with being in space." (PMID 31547269, 2019).
lung carcinoma (5 papers, 2007 to 2025). "Betta-tubulin, TUBB, gene is implicated in many cancers including ovarian and lung cancer." (PMID 19455236, 2007). "Additionally, CHEK1 has been shown to regulate TUBB protein levels, in which CHEK1 overexpression was shown to increase TUBB protein levels in lung cancer cell lines." (PMID 36140469, 2022). "The DEGs centrally had direct interaction with EGFR, ERBB2, ERBB4, MET and TUBB, which suggested that the divergence between the primary CRC and the metastases of CRC was related to lung cancer." (PMID 30642283, 2019). "Although the role of TUBB in mediating immune cell infiltration has not been investigated extensively, several members of the tubulin family have been shown to play a role in immune cell infiltration including TUBA1C, which mediates immune infiltration in lung cancer." (PMID 36140469, 2022).
melanoma (5 papers, 2015 to 2025). A malignant, usually aggressive tumor composed of atypical, neoplastic melanocytes. "Based on correlation analysis between PDC6IP and 83 MTEX proteins differentiating melanoma patients with PD from those with NED/SD, we found four proteins that strongly (ru > 0.7, P < 0.005) associated with PDC6IP, namely HSP90AB1, PFN1, TUBB, and TUBB1." (PMID 33613873, 2021). "TUBB, TUBB1, TUBB2A, TUBB4A and TUBB4B belong to the tubulin family, and gene expression analyses showed a higher expression of all these tubulins in melanoma compared to normal skin." (PMID 37291228, 2023). "Hence, the molecular signature of MTEX consisting of PDCD6IP/ALIX, 4 correlated proteins (HSP90AB1, TUBB, TUBB1, and PFN1) highly expressed in MTEX of patients with PD, plus CNTN1 and TGF‐β1 with differential distribution in MTEX of PD vs NED/SD patients may have prognostic significance in melanoma." (PMID 33613873, 2021).
tubulinopathies (5 papers, 2015 to 2021). "Recent analysis performed on TUBA1A loss-of-function mice and cultured fibroblasts from TUBB-associated tubulinopathy patients have revealed an impaired MT dynamics and aberrant cytoskeleton configurations in the axonal GCs." (PMID 34924953, 2021). "Other mutations in human α-and β-tubulin-encoding genes – such as TUBA1A, TUBB2B, TUBA8, TUBB4A, TUBB2A, TUBB – are linked to severe brain malformations and motor-cognitive disabilities, collectively refereed as tubulinopathies." (PMID 34924953, 2021). "Complex brain malformations associated with dominant or de novo missense mutations in tubulin genes TUBA1A, TUBB2B, TUBB3, TUBB or TUBG1 are commonly referred to as “tubulinopathies”." (PMID 32085672, 2020). "The variability of patient phenotypes underscores the possibility, seen in other tubulinopathies, that specific TUBB mutations may have different impacts on MT functions." (PMID 32085672, 2020). "Overall, our comparative analysis of fibroblast cell lines derived from patients harboring different mutations in TUBB, and presenting clinically distinct phenotypes, provides further insights into cellular defects caused by MT dysfunction underlying the phenotypic variability of tubulinopathies." (PMID 32085672, 2020). "Other “tubulinopathies” genes include TUBA1A, TUBB2A, TUBB2B, TUBA8, TUBB3, TUBB, and TUBG1, which were found to be DEGAs in various brain regions." (PMID 34638726, 2021).
colorectal cancer (4 papers, 2014 to 2025). A primary or metastatic malignant neoplasm that affects the colon or rectum. "This change in expression pattern suggests that TUBB might be associated with the malignancy of colorectal cancer epithelial cells." (PMID 40539065, 2025). "To further investigate the clinical significance of TUBB, we obtained paired clinical tissue samples from colorectal cancer patients at Yangpu Hospital, utilizing these for Western Blot (n=59) and quantitative Reverse Transcription Polymerase Chain Reaction (qRT-PCR) analyses (n=35)." (PMID 40539065, 2025). "Meanwhile, there have been no previous studies on the role of TUBB in colorectal cancer." (PMID 40539065, 2025).
microcephaly (4 papers, 2018 to 2022). A congenital or acquired developmental disorder in which the circumference of the head is smaller than normal for the person's age and sex. "Patients with TUBB mutations exhibit neurological features including microcephaly, dysgenesis of the cerebellum and the basal ganglia, agenesis of the corpus callosum and congenital symmetrical circumferential skin creases (CSC-KT)." (PMID 32085672, 2020). "Patients with mutations in TUBB have circumferential skin creases Kunze type (CSC-KT) which includes circumferential skin creases, microcephaly, cleft palate, intellectual disability and other associated anomalies but also structural brain anomalies are described." (PMID 34358225, 2021). "The association between microcephaly, polymicrogyria and cerebellar agenesis prompted us to screen for tubulin genes (TUBA1A, TUBA8, TUBB2A, TUBB2B, TUBB3, TUBB4A, TUBB, TUBG1), which were all negative." (PMID 35162247, 2022).
non-small cell lung carcinoma (4 papers, 2005 to 2024). A group of at least three distinct histological types of lung cancer, including non-small cell squamous cell carcinoma, adenocarcinoma, and large cell carcinoma. "A previous study has demonstrated that mutations of TUBB are closely associated with both chemoresistance and worse overall survival in non-small-cell lung cancer." (PMID 32461969, 2020). "A previous genetic analysis indicated a strong association of the TUBB gene with non-small-cell lung cancer." (PMID 24099319, 2013).
osteosarcoma (4 papers, 2015 to 2024). A usually aggressive malignant bone-forming mesenchymal neoplasm, predominantly affecting adolescents and young adults. "In osteosarcoma, TUBB has been identified as the significant survival-predicting factor." (PMID 38756529, 2024). "The TUBB protein was found to be downregulated in osteosarcoma samples." (PMID 39980969, 2024). "Direct co-regulation has been observed between TUBB, RPLPO and ACTB via v-myc myelocytomatosis viral (MYCN) and between TUBB and RPLPO via FBJ murine osteosarcoma viral (FOS)." (PMID 25881111, 2015). "Accordingly, in osteosarcoma, TUBB and MAP3K5 were believed to function as tumor suppressors, actively inhibiting tumor growth and progression, while TERT and PPARG appear to act as cancer promoters, exacerbating the development of osteosarcoma." (PMID 39980969, 2024).
pancreatic cancer (4 papers, 2020 to 2025). "Although the crosstalk between TUBB and Rho/ROCK signaling pathway has not been studied extensively, TUBB has been shown to activate the Rho/ROCK signaling pathway that mediates pancreatic cancer proliferation and metastasis." (PMID 36140469, 2022). "Tubulin beta 3 class III (TUBB3), but not tubulin beta class I (TUBB) or tubulin beta 2 A-C class IIa, IIb, IIc (TUBB2A-C), plays critical roles in pancreatic tumor growth and metastasis." (PMID 39962586, 2025).